ZFP82 (ZFP82 zinc finger protein)
Description:
May be involved in transcriptional regulation.
Synonyms: KIAA1948; ZNF545; MGC45380
Tractability: PROTAC: UniProt records ubiquitination sites on it; ubiquitination databases record sites on it.
Gene: Protein-coding gene on chromosome 19 (36,383,120 to 36,418,667, reverse strand). Ensembl gene ENSG00000181007.
Subcellular location: Nucleus
Subcellular location (Human Protein Atlas): Cytosol; Nucleoplasm; Nuclear membrane
Gene Ontology:
Molecular function: DNA-binding transcription factor activity, RNA polymerase II-specific; RNA polymerase II cis-regulatory region sequence-specific DNA binding
Biological process: regulation of transcription by RNA polymerase II; regulation of DNA-templated transcription
Cellular component: nucleus
Genetic constraint (gnomAD): Loss-of-function variants: 28 observed, 53.36 expected, observed/expected ratio (o/e) 0.52, 90% interval 0.39 to 0.72. The upper end of that interval is the gene's LOEUF score, 0.72, which puts it in group 2 of 6, group 1 being the genes least tolerant of losing a copy. Missense variants: 488 observed, 655.67 expected, observed/expected ratio (o/e) 0.74, 90% interval 0.69 to 0.8. Synonymous variants: 189 observed, 216.16 expected, observed/expected ratio (o/e) 0.87, 90% interval 0.78 to 0.99.
Homologues: Orthologues: chimpanzee ZFP82 (100% identical), macaque ZFP82 (99% identical), pig ZFP82 (92% identical), mouse Zfp82 (85% identical), rabbit ZFP82 (84% identical), rat Zfp82 (84% identical). Paralogues in human: ZFP30 (75% identical), ZFP14 (70% identical), ZNF546 (56% identical), ZNF540 (54% identical), ZNF571 (54% identical), ZNF30 (52% identical), ZNF573 (52% identical), ZNF780B (51% identical), ZNF461 (50% identical), ZNF595 (48% identical), ZFP28 (47% identical), ZNF528 (47% identical), and 164 more.
Diseases named in the same sentence as ZFP82 in open-access papers:
ZFP82 is named in the same sentence as 17 diseases in open-access papers, as found by Europe PMC text mining. Sharing a sentence is not in itself a finding about the gene and the disease. The quoted sentences say what the papers report.
gastric cancer (5 papers, 2015 to 2023). A primary or metastatic malignant neoplasm involving the stomach. "Thus, highlighting the potential of the methylated CpG site of the ZFP82 promoter as a clinical predictor of gastric cancer prognosis." (PMID 33833773, 2021).
multiple myeloma (3 papers, 2017 to 2021). "Besides, tumor-specific methylation of ZFP82 has been implicated in multiple myeloma, with studies suggesting their potential as epigenetic biomarkers for the diagnosis of multiple myeloma as well as a promising target for specific treatment." (PMID 33833773, 2021).
colorectal cancer (2 papers, 2021). A primary or metastatic malignant neoplasm that affects the colon or rectum. "The inhibition of ZFP82 though promoter methylation has been detected in colorectal cancer, which also possesses tumor-suppressing properties in the setting of colorectal cancer." (PMID 33833773, 2021).
pancreatic cancer (2 papers, 2021 to 2024). "The key findings of the current study highlights ZNF804A, ZFP82, TRIM58, SOX17, and C12orf42 as hypermethylated/downregulated genes in pancreatic cancer associated with the development and progression of pancreatic cancer through their modulation of specific pathways." (PMID 33833773, 2021). "Taken together, the key findings of the current study demonstrate that ZNF804A, ZFP82, TRIM58, SOX17, and C12orf42 are hypermethylated/downregulated genes in pancreatic cancer and may be associated, through their modulation of specific pathways, with unfavorable pancreatic cancer prognosis." (PMID 33833773, 2021). "TMPRSS4 and ZFP82, have been shown to induce Epithelial-to-Mesenchymal transition (EMT) in pancreatic cancer." (PMID 38902676, 2024). "Univariate Cox model and Kaplan–Meier method revealed that, among 31 MeDEGs, 5 hypermethylated/downregulated genes (ZNF804A, ZFP82, TRIM58, SOX17, and C12orf42) were correlated with poor survival of patients with pancreatic cancer." (PMID 33833773, 2021). "In the current study, 5 hypermethylated/downregulated genes in pancreatic cancer were identified, including ZNF804A, ZFP82, TRIM58, SOX17, and C12orf42, all of which were found to be correlated with the poor survival of pancreatic cancer patients." (PMID 33833773, 2021).
esophageal cancer (1 paper, 2025). A primary or metastatic malignant neoplasm involving the esophagus. "Our previous research found that the promoter of zinc-finger protein 82 (ZFP82) was highly methylated in multiple cancers, including esophageal cancer, which induces the occurrence and development of tumors." (PMID 41053060, 2025).
esophageal squamous cell carcinoma (1 paper, 2021). Esophageal squamous cell carcinoma (ESCC) is a type of esophageal carcinoma (EC) that can affect any part of the esophagus, but is usually located in the upper or middle third. "Previous literature has highlighted the downregulation of ZFP82 through promoter methylation in esophageal squamous cell carcinoma, which is associated with age, tumor stage as well as the prognosis of squamous cell carcinoma." (PMID 33833773, 2021).
tumor (15 papers, 2014 to 2025). "ZFP82, also known as ZNF545, belongs to the Kruppel-related box zinc finger protein family, which is often down-regulated by promoter methylation serves as a tumor-suppressor gene in a variety of cancers." (PMID 33833773, 2021). "ZFP82 codes for a zinc finger transcription factor that displays tumor suppressor properties." (PMID 37026480, 2023). "Among which, the hypermethylation of ZNF804A, ZFP82, TRIM58, SOX17, and C12orf42 were all noted to be significantly associated with tumor-related pathways, including calcium signaling pathways, neuroactive ligand-receptor interaction, glycosynthetic ganglion series and intercellular junctions." (PMID 33833773, 2021).
cancer (7 papers, 2014 to 2025). A tumor composed of atypical neoplastic, often pleomorphic cells that invade other tissues. "In addition, the strict scale in the present study to only analyze the proteins detected in all examined samples ruled out some important DEPs such as cancer-related proteins, which changed dramatically during carcinogenesis, such as Cacna1b, Col15a1, Hmgcr, Zfp82, and Znrd1-as." (PMID 32792008, 2020).
ZFP82 also shares sentences with these, for which no sentence is quoted: breast carcinoma (2 papers); colon cancer (2); astrocytoma (1); breast tumor (1); colorectal (1); gastric tumour (1); hepatocellular carcinoma (1); oral cancer (1); squamous cell carcinoma (1).